MIR3118-3 (microRNA 3118-3)
Synonyms: hsa-mir-3118-3
Gene: MicroRNA gene on chromosome 15 (21,406,385 to 21,406,459, forward strand). Ensembl gene ENSG00000277243.
Homologues: Paralogues in human: MIR3118-2 (100% identical), MIR3118-4 (100% identical).